GPR4 (G protein-coupled receptor 4)
Diseases named in the same sentence as GPR4 in open-access papers (continued):
Sharing a sentence is not in itself a finding about the gene and the disease.
myocardial infarction (7 papers, 2017 to 2023). Gross necrosis of the myocardium, as a result of interruption of the blood supply to the area, as in coronary thrombosis. "In this context, a dibenzazepine derivate has been described as a potent GPR4 antagonist that reduced mortality in a mouse myocardial infarction model in which mice were subjected to permanent ligation of the left anterior descending coronary." (PMID 34440817, 2021). "The recent demonstration of antinociceptive activity of NE 52-QQ57 highlights a potential avenue for exploration, as does the potential application of another GPR4 antagonist for treatment of myocardial infarction." (PMID 29894771, 2018). "Other similar GPR4 inhibitors have also been shown to reduce acidosis-induced EC inflammation and promote survival in a mouse myocardial infarction model." (PMID 28134810, 2017). "A recent study further demonstrates that treatment with a GPR4 inhibitor prolongs animal survival in a myocardial infarction mouse model." (PMID 28134810, 2017). "Previously, the pharmacological inhibition of GPR4 was reported to remediate myocardial infarction, and the genetic deletion of GPR4 improved cardiac function by lowering blood pressure and inhibited apoptosis, which reduced renal ischemia reperfusion injury and intestinal inflammation." (PMID 33925146, 2021). "In the cardiovascular context, GPR4 was shown to be activated upon ischemic stress and pH decrease, and GPR4 may influence myocardial infarction originated from ischemic stress and subsequent pH decrease." (PMID 34440817, 2021).
colorectal cancer (6 papers, 2020 to 2025). A primary or metastatic malignant neoplasm that affects the colon or rectum. "GPR4 expression is increased in patients with inflammatory bowel disease who are at high risk of developing colorectal cancer." (PMID 40397803, 2025). "Experiments with GPR4-deficient mice showed reduced tumor angiogenesis and tumor growth in an orthotopic tumor model using the murine colorectal carcinoma cell line CT26." (PMID 38514581, 2024). "GPR4 expression is associated with increased angiogenesis in hepatocellular, head and neck, breast, and colorectal cancers." (PMID 37894341, 2023). "The results of this study show that loss of pH‐sensing receptor GPR4 reduces colorectal cancer cell growth in vivo, both in a model ectopically implanted MC38 colon carcinoma cells, as well as during spontaneous tumor development and growth in the AOM/DSS model." (PMID 40397803, 2025). "Also, GPR4 deficiency curtailed tumor growth and angiogenesis in one colitis-associated colorectal cancer mouse model." (PMID 39336742, 2024). "GPR4 expression was found to be upregulated in colorectal tumor samples and GPR4 signaling promoted colorectal cancer cell proliferation and metastasis through the Hippo pathway." (PMID 39336742, 2024). "Collectively, the genetic deletion of GPR4 likely halts colorectal cancer development by dampening chronic intestinal inflammation and impeding tumor angiogenesis." (PMID 37894341, 2023). "Herein, using wild-type and GPR4 knockout mouse CAC models, we investigated the role of GPR4 in inflammation-driven colorectal cancer." (PMID 37894341, 2023). "Zhong M's research found that the proton‐sensing receptor GPR4 is highly expressed in colorectal cancer, and GPR4 can promote the metastasis of colorectal cancer cells by inhibiting LATS activity and YAP1 nuclear translocation." (PMID 33090721, 2020). "In addition, GPR4 has a protumorigenic role in hepatocellular, head and neck, breast, and colorectal cancers." (PMID 37894341, 2023).
inflammatory bowel disease (6 papers, 2019 to 2025). A spectrum of small and large bowel inflammatory diseases of unknown etiology. "Additionally, GPR4-deficiency reduces intestinal inflammation in a murine colitis model and in a model of inflammatory bowel disease (IBD)." (PMID 34440817, 2021). "Intestinal tissue from patients with inflammatory bowel disease (IBD) shows increased expression of GPR4." (PMID 40397803, 2025). "Interestingly, GPR4 mRNA is over-expressed by approximately 5-fold in the inflamed intestinal lesions of inflammatory bowel disease (IBD) patients when compared to normal intestinal tissues." (PMID 33553219, 2020). "GPR4 and GPR65 have both been attributed functions in inflammatory bowel disease (IBD)." (PMID 38374228, 2024). "GPR4 also plays a significant role in the regulating of intestinal inflammation, as was identified in inflammatory bowel disease models using mice lacking GPR4." (PMID 31683697, 2019).
osteoarthritis (6 papers, 2022 to 2025). A noninflammatory degenerative joint disease occurring chiefly in older persons, characterized by degeneration of the articular cartilage, hypertrophy of bone at the margins and changes in the synovial membrane. "Consistent with a role for GPR4 in the development of osteoarthritis is the finding that advanced glycation end products, which have been linked to osteoarthritis, increase GPR4 expression." (PMID 38340167, 2024). "Moreover, overexpression of GPR4 accelerated the development of posttraumatic and ageing-associated osteoarthritis in mice whilst GPR4 ko had the opposite effect." (PMID 38340167, 2024). "The GPR4 antagonist NE-52-QQ57 alleviated mouse osteoarthritis progression and promoted extracellular matrix production." (PMID 39336742, 2024). "CCR2, GPR4, α2A-AR, and CaSR will accelerate the progression of osteoarthritis." (PMID 40860192, 2025). "Additionally, GPR4 overexpression promotes the development of osteoarthritis (OA), and the pharmacological inhibition of GPR4 protects mice against OA via regulating the CXCL12/CXCR7 pathway." (PMID 39336742, 2024).
Arthritis (5 papers, 2020 to 2025). Inflammation of a joint. "The GPR4 antagonist compound 13 also reduced inflammation in arthritis models and angiogenesis in mouse implanted models." (PMID 38505262, 2024). "GPR4 was found to be involved in chronic inflammatory pain and GPR4-inhibitors could reduce arthritis-induced inflammatory pain in a rodent model." (PMID 34440817, 2021). "Compound 39c, also a GPR4 antagonist, reduced VEGF-induced angiogenesis and alleviated arthritis pain in rats." (PMID 38505262, 2024). "As shown in the hindlimb ischemia-reperfusion, arthritis, and COPD animal models, inhibition of GPR4 can reduce vessel permeability and tissue edema." (PMID 33553219, 2020).
breast carcinoma (4 papers, 2013 to 2023). "Another study demonstrated the reduced growth of orthotopic breast cancer and colon cancer allografts in GPR4 KO mice due to decreased angiogenesis." (PMID 37894341, 2023). "A few genes previously reported to be induced by acidosis in breast cancer cells, including TXNIP, ARRDC4 and EGR2, were also noted to be induced in both HUVEC/Vector and HUVEC/GPR4 cells." (PMID 23613998, 2013).
colon carcinoma (4 papers, 2016 to 2025). "Similarly, it was recently shown that intestinal inflammation, colon cancer development, and tumor angiogenesis were decreased in Gpr4‐deficient animals compared to wild‐type (WT) controls." (PMID 40397803, 2025). "In this study, we aimed to better understand the physiological role of GPR4 in tumorigenesis in animal models of colon cancer." (PMID 40397803, 2025). "To study the role of GPR4 in colon cancer progression, we injected MC38 colon adenocarcinoma cells into mice lacking GPR4 expression." (PMID 40397803, 2025). "Gpr4‐deficient and WT mice were used in the subcutaneously (s.c.)MC38 injection model and the AOM/DSS‐induced colon cancer model." (PMID 40397803, 2025). "Moreover, blood vessel density positively correlated with tumor volume and negatively correlated with tumor necrosis area in the WT AOM/DSS and GPR4 KO AOM/DSS mouse colon tumors." (PMID 37894341, 2023). "This protumoral effect may be related with a proangiogenic activity since colonic tumors from GPR4-KO mice presented an altered vessel morphology, length and density and GPR4-transfected cells promoted the formation of tubes by human microvascular endothelial cells in a paracrine manner in vitro." (PMID 33113952, 2020). "A significant increase in colon tumor number was observed in the WT AOM/DSS mice when compared with the GPR4 KO AOM/DSS mice, suggesting GPR4 promotes CAC development." (PMID 37894341, 2023). "The MC38 s.c. injection model allows us to assess engraftment and growth of established colon cancer cells, yet it does not allow us to study the role of GPR4 in early tumor development, which in the case of CRC can be driven by inflammation." (PMID 40397803, 2025). "Our data show that the absence of functional GPR4 in the tumor microenvironment reduces colon cancer growth." (PMID 40397803, 2025).
COVID-19 (4 papers, 2020 to 2025). A disease caused by infection with severe acute respiratory syndrome coronavirus 2. "In this context, Yang and colleagues hypothesized that GPR4, a pro-inflammatory receptor, may be implicated in the pathophysiology of COVID-19 and could be a potential therapeutic target to improve COVID-19-related complications." (PMID 36189213, 2022). "Deletion of GPR4 is associated with lower blood pressure, lower binding to angiotensin II receptor, and increased insulin sensitivity; these aspects are of particular interest as hypertension and diabetes are risk factors associated with COVID-19 mortality." (PMID 33553219, 2020). "Fifth, GPR4 antagonists may alleviate pain associated with COVID-19." (PMID 33553219, 2020). "In line with previous findings that GPR4 expression is upregulated in lung and colon tissues of COVID-19 patients, we observed an increase in GPR4 expression in the K18-hACE2 mouse lung following SARS-CoV-2 infection." (PMID 40703349, 2025). "Our results demonstrated that GPR4 antagonist treatment increased the survival rate in this severe COVID-19 mouse model." (PMID 40703349, 2025). "Animals administered with the GPR4 antagonist exhibited an increased survival rate compared to those in the vehicle control group in this severe COVID-19 mouse model." (PMID 40703349, 2025). "This pharmacological feature of the GPR4 antagonist can be advantageous for the treatment of COVID-19, as the reduction in both viral load and hyperinflammatory response is necessary for optimal management of COVID-19 related complications." (PMID 40703349, 2025). "Most recently, a pro-inflammatory role for GPR4 has been proposed in COVID-19, where GPR4 gene expression was found to be upregulated in COVID-19 patients’ lung and colon samples by 2.3-fold and 3.9-fold, respectively." (PMID 39336742, 2024). "Based on the effects of GPR4 antagonists in other disease models, inhibition of GPR4 can be explored as a novel approach to mitigate COVID-19 complications." (PMID 33553219, 2020). "Therefore, we hypothesize that GPR4 antagonism can potentially be exploited to mitigate the hyper-inflammatory response, vessel hyper-permeability, pulmonary edema, exudate formation, vascular thromboembolism and tissue injury associated with COVID-19." (PMID 33553219, 2020). "Compared to normal lung and colon samples, GPR4 mRNA levels were increased by 2.3-fold (p = 3.04E-06) and 3.9-fold (p = 0.0074), respectively, in COVID-19 patient lung and colon samples." (PMID 33553219, 2020). "We propose that GPR4 is involved in COVID-19 pathophysiology and can be exploited as a potential therapeutic target for COVID-19." (PMID 33553219, 2020). "All these biological functions of GPR4 are highly relevant to COVID-19 patient pathophysiology, including the hyper-inflammatory response, leukocyte infiltration, blood vessel leakage, pulmonary edema, and vascular thromboembolism." (PMID 33553219, 2020). "Based on its biological functions, GPR4 can potentially regulate multiple aspects of COVID-19 pathophysiology." (PMID 33553219, 2020). "Together, these results suggest that GPR4 antagonism may be explored as a novel approach for the treatment of COVID-19 and other similar viral diseases." (PMID 40703349, 2025). "Altogether, the findings suggest that GPR4 is a pro-inflammatory receptor involved in COVID-19 and GPR4 antagonism may be exploited as a potential therapeutic approach to dampen the hyperinflammatory response of COVID-19 to alleviate disease severity." (PMID 40703349, 2025). "It is also crucial to investigate whether the GPR4 antagonist exhibits anti-inflammatory and anti-viral effects in other similar viral diseases in addition to COVID-19." (PMID 40703349, 2025). "The gene expression of GPR4 is upregulated in COVID-19 patient lung and colon tissues." (PMID 40703349, 2025).
COVID-19 (continued). "Additionally, a correlation has been identified between GPR4 RNA expression obtained from patient nasal swabs at the time of testing and COVID-19 severity at a later stage." (PMID 39336742, 2024). "GPR4 antagonists can potentially curtail angiogenesis in COVID-19." (PMID 33553219, 2020). "Herein, we hypothesize that GPR4 plays an integral role in COVID-19 pathophysiology and is a potential therapeutic target for the treatment of COVID-19." (PMID 33553219, 2020). "In addition to inflammatory responses, the effects of GPR4 antagonists on other COVID-19 complications such as blood vessel permeability, lung edema, vascular thromboembolism, and pain can also be evaluated in these preclinical animal models." (PMID 33553219, 2020). "Inhibition of GPR4 can potentially mitigate inflammatory pain in COVID-19 patients." (PMID 33553219, 2020). "Herein, we evaluate the potential involvement of GPR4 in the pathophysiology of COVID-19." (PMID 33553219, 2020). "GPR4 antagonists potentially target several key aspects of COVID-19 pathophysiology." (PMID 33553219, 2020). "The up-regulation of GPR4 gene expression in COVID-19 patient tissues may further aggravate the GPR4-mediated pro-inflammatory effects and contribute to COVID-19 pathophysiology." (PMID 33553219, 2020). "Second, GPR4 antagonists may reduce vascular leakage, tissue edema and inflammatory exudate formation in COVID-19." (PMID 33553219, 2020). "We hypothesize that GPR4 plays an integral role in COVID-19 pathophysiology and inhibition of GPR4 can be explored as a novel approach to mitigate COVID-19 complications." (PMID 33553219, 2020). "First, GPR4 antagonists may inhibit inflammatory responses and leukocyte infiltration in the lung and other affected organs of COVID-19 patients." (PMID 33553219, 2020). "Moreover, GPR4 gene expression is up-regulated in COVID-19 patient samples." (PMID 33553219, 2020). "Therefore, we hypothesize that GPR4 plays a role in COVID-19 pathophysiology and GPR4 antagonism is a potential therapeutic approach to mitigate COVID-19 complications." (PMID 33553219, 2020). "Fourth, GPR4 antagonists may decrease angiogenesis in COVID-19." (PMID 33553219, 2020). "Third, GPR4 antagonists may attenuate vascular thromboembolism in COVID-19." (PMID 33553219, 2020). "Therefore, we hypothesized that GPR4 plays an integral role in COVID-19 pathophysiology." (PMID 40703349, 2025). "Our results demonstrated that the GPR4 antagonist reduced the inflammatory response and SARS-CoV-2 viral load and increased the survival rate in this severe COVID-19 murine model." (PMID 40703349, 2025).
Anxiety (3 papers, 2018 to 2024). Intense feelings of nervousness, tension, or panic often arise in response to interpersonal stresses. "Many of the nuclei shown to express GPR4 in this study have been implicated in the manifestation and control of anxiety." (PMID 38408869, 2024). "The biological significance of GPR4 expression in multiple neuronal populations requires further investigation, especially given the association of some of these nuclei with anxiety and responses to stress." (PMID 29894771, 2018). "Aside from its demonstrated contribution to respiratory chemosensitivity via RTN neurons, the role of GPR4 in additional CO2/H+-sensitive processes (e.g., arousal, anxiety) mediated by other GPR4-expressing neurons remains to be determined." (PMID 38408869, 2024). "Ablation of the cholinergic neurons of the ventral portion of the MHb, which are the cells shown to express GPR4, leads to increased fear behavior and higher baseline anxiety." (PMID 38408869, 2024). "Chemo- and optogenetic activation of the GABAergic neurons in the lateral septum, in the same area as the cells found to express GPR4 in this study, induces anxiety behaviors in mice." (PMID 38408869, 2024). "It is unclear how activation of the MHb by GPR4 during hypercapnia would lead to the increased anxiety and freezing behavior observed, given the seemingly contradictory observations noted in ablation studies; perhaps GPR4 signaling inhibits the activity of cholinergic MHb neurons." (PMID 38408869, 2024). "It is possible that the expression of GPR4 by these anxiety-initiating neurons in the lateral septum may mediate some of the anxiogenic effects of CO2." (PMID 38408869, 2024). "It is possible that GPR4 acts more broadly to tune the overall anxiety system during hypercapnia and not in activating distinct nuclei." (PMID 38408869, 2024). "Anxiety phenotypes have not yet been reported in GPR4 knock-out mice." (PMID 38408869, 2024). "Additionally, there is significant crossover between efferents and afferents of the GPR4-expressing forebrain nuclei; for example, both the lateral septum and medial habenula project to the dopaminergic neurons of the ventral tegmental area (VTA), whose activation induces anxiety behaviors." (PMID 38408869, 2024).
head and neck cancer (3 papers, 2016 to 2023). A primary or metastatic malignant neoplasm affecting the head and neck. "Interestingly, it has also been reported that GPR4 expression is increased in hepatocellular carcinoma, head and neck cancer, and CRC tissues compared with normal tissues." (PMID 37894341, 2023).
Parkinson disease (3 papers, 2020 to 2024). A progressive degenerative disorder of the central nervous system characterized by loss of dopamine producing neurons in the substantia nigra and the presence of Lewy bodies in the substantia nigra and locus coeruleus. "GPR4 has been linked to two neurodegenerative conditions, Alzheimer’s disease and Parkinson’s disease." (PMID 38340167, 2024). "In this study, we used the administration of a subchronic MPTP dose to induce Parkinsonism in C57BL/6J mice to further explore the role played by GPR4 in the induction of classical mitochondrial apoptotic cell death." (PMID 33925146, 2021). "Therefore, GPR4 presents a potential therapeutic target for neurodegenerative disorders such as Parkinson’s disease." (PMID 33053856, 2020). "This study explored the role of GPR4 in a 1-methyl-4-phenyl-1,2,3,6-tetrahydropyridine (MPTP)-treated mouse model of Parkinson’s disease (PD)." (PMID 33925146, 2021). "In a chemically induced mouse model of Parkinson’s disease, lack of GPR4 expression was shown to be neuroprotective in dopaminergic neurons, and pharmacological inhibition of GPR4 not only reduced neuronal apoptosis but also improved motor and memory functions." (PMID 38340167, 2024).
breast tumors (2 papers, 2010 to 2022). "Interestingly, GPR4 was not overexpressed in breast tumors compared with normal breast tissue." (PMID 35545051, 2022).
colorectal tumor (2 papers, 2023 to 2024). "Increased GPR4 expression has been observed in colorectal tumors compared with adjacent normal tissue and is associated with decreased overall survival in patients." (PMID 37894341, 2023). "We found that GPR4 is expressed in the vascular endothelial cells of colorectal tumors in AOM/DSS mice and may be involved in tumor vascularization." (PMID 37894341, 2023).
coronary artery disease (2 papers, 2021 to 2024). "Furthermore, loss of GPR4 function has been linked to lack of acidosis-mediated growth of new blood vessels in patients with coronary artery disease, who display lower GPR4 expression levels in endothelial progenitor cells than healthy individuals." (PMID 38340167, 2024).